GDAP1 (ganglioside induced differentiation associated protein 1)
Description:
Regulates the mitochondrial network by promoting mitochondrial fission.
Synonyms: CMT4; CMT2K; CMT4A; CMTRIA
Tractability: Small molecule: a structure with a bound ligand is known. Antibody: UniProt predicts a signal peptide or a membrane-spanning region. PROTAC: UniProt records ubiquitination sites on it; ubiquitination databases record sites on it; its protein half-life has been measured.
Gene: Protein-coding gene on chromosome 8 (74,320,613 to 74,518,007, forward strand). Ensembl gene ENSG00000104381.
Subcellular location: Mitochondrion outer membrane; Cytoplasm
Subcellular location (Human Protein Atlas): Mitochondria; Cytosol
Pathways (Reactome):
Protein localization: Class I peroxisomal membrane protein import
Gene Ontology:
Molecular function: protein binding
Biological process: mitochondrial fission; mitochondrial fusion; cellular response to vitamin D
Cellular component: membrane; mitochondrial outer membrane; mitochondrion; nucleus; cytoplasm; cytosol; peroxisomal membrane
Genetic constraint (gnomAD): Loss-of-function variants: 17 observed, 26.48 expected, observed/expected ratio (o/e) 0.64, 90% interval 0.44 to 0.96. The upper end of that interval is the gene's LOEUF score, 0.96, which puts it in group 4 of 6, group 1 being the genes least tolerant of losing a copy. Missense variants: 305 observed, 366.38 expected, observed/expected ratio (o/e) 0.83, 90% interval 0.76 to 0.92. Synonymous variants: 140 observed, 134.98 expected, observed/expected ratio (o/e) 1.04, 90% interval 0.9 to 1.19.
Gene-disease validity (ClinGen):
ClinGen rates the evidence that GDAP1 causes each of these diseases.
Charcot-Marie-Tooth disease (semidominant): Definitive. An inherited degenerative disorder involving the peripheral nerves.
Homologues: Orthologues: chimpanzee GDAP1 (99% identical), macaque GDAP1 (99% identical), dog GDAP1 (97% identical), pig GDAP1 (96% identical), rabbit GDAP1 (96% identical), mouse Gdap1 (94% identical), guinea pig GDAP1 (93% identical), rat Gdap1 (93% identical), tropical clawed frog gdap1 (76% identical), zebrafish gdap1 (71% identical), Drosophila melanogaster GstE11 (15% identical), Drosophila melanogaster GstE12 (15% identical), and 29 more. Paralogues in human: GDAP1L1 (54% identical), GSTT2B (17% identical), GSTT2 (17% identical), EEF1G (15% identical), CLIC1 (13% identical), CLIC6 (13% identical), CLIC4 (13% identical), GSTT4 (12% identical), CLIC2 (12% identical), CLIC5 (12% identical), CLIC3 (12% identical), GSTZ1 (10% identical), and 2 more.
Diseases named in the same sentence as GDAP1 in open-access papers:
GDAP1 is named in the same sentence as 55 diseases in open-access papers, as found by Europe PMC text mining. Sharing a sentence is not in itself a finding about the gene and the disease. The quoted sentences say what the papers report.
Charcot-Marie-Tooth disease (27 papers, 2009 to 2026). "Pathogenic variants of GDAP1 cause Charcot-Marie-Tooth disease (CMT), an inherited neuropathy characterized by axonal degeneration." (PMID 39801517, 2024). "Pathogenic variants in the GDAP1 gene cause Charcot-Marie-Tooth (CMT) disease, a motor and sensory neuropathy, which is the most common hereditary neuromuscular disorder." (PMID 36912213, 2023). "GDAP1 pathogenic variants cause Charcot-Marie-Tooth (CMT) disease, the most common hereditary motor and sensory neuropathy." (PMID 36912213, 2023). "Inherited JPH1 variants act as a disease-modifier in Charcot-Marie-Tooth disease caused by variants in ganglioside-induced differentiation-associated protein 1 (GDAP1)." (PMID 35001666, 2022). "More than 80 mutations in GDAP1 gene have already been reported to be responsible for demyelinating, axonal, and intermediate forms of Charcot-Marie-Tooth disease, and associated to heterogeneous phenotypic manifestations." (PMID 34440148, 2021). "The GDAP1 mutation induced progression to peripheral nerve injury Charcot-Marie-Tooth disease, with primary axonal damage and primary dehydration of the peripheral nerve." (PMID 30563106, 2018). "Mutations in the ganglioside-induced differentiation associated protein 1 (GDAP1) cause severe peripheral motor and sensory neuropathies called Charcot-Marie-Tooth disease." (PMID 27841286, 2016). "Mutations of GDAP1 gene cause autosomal dominant and autosomal recessive Charcot-Marie-Tooth disease and more than 40 different mutations have been reported." (PMID 26848201, 2015). "Mutations in the gene GDAP1 are involved in the Charcot-Marie-Tooth disease (CMT) type 2 K and 4 A in humans that is characterized by progressive hypo- and demyelination resulting in motor and sensory neuropathy." (PMID 24324618, 2013). "This study suggests that GDAP1 variants may be associated with very mild, predominantly sensory Charcot-Marie-Tooth disease, warranting continuing research for this type of the disease." (PMID 35656516, 2022). "Mutations in GDAP1 (ganglioside-induced differentiation protein 1) gene have been reported for the first time in 2001, and are well known to induce multiple types of Charcot-Marie-Tooth disease." (PMID 34440148, 2021). "Mutations in the GDAP1 gene, coding for the ganglioside-induced differentiation-associated protein 1 (GDAP1), are associated with several forms of Charcot-Marie-Tooth disease (CMT), which is one of the most common inherited neurological disorders, affecting one in 2,500 people." (PMID 33585569, 2020). "Interestingly, dysregulation of SOC channels has also been implicated in another inherited peripheral neuropathy, Charcot-Marie-Tooth disease, secondary to GDAP1 mutations." (PMID 29778900, 2018). "Mutations in the GDAP1 gene can cause Charcot-Marie-Tooth disease." (PMID 28751717, 2017). "Genetic variants in GDAP1 cause Charcot-Marie-Tooth disease (CMT), emphasizing its essential role in peripheral nerve function." (PMID 41750352, 2026). "Besides MFN2, Charcot-Marie-Tooth disease can be further caused by mutations in GDAP1." (PMID 34295920, 2021). "Variants in GDAP1 produce both dominant and recessive forms of Charcot-Marie-Tooth disease (CMT), a group of motor or sensory neuropathy diseases." (PMID 33426505, 2020). "Mutations in GDAP1 lead to the peripheral neuropathy Charcot-Marie-Tooth disease (CMT), affecting both Schwann cells, the myelinating glia of the peripheral nervous system, and neurons." (PMID 19340293, 2009). "Since Charcot-Marie-Tooth disease is peripheral neuropathy, we evaluated indicative parameters of oxidative stress in spinal cords and sciatic nerves of six-month-old wild-type and Gdap1−/− mice." (PMID 39801517, 2024). "Mutations in the ganglioside-induced differentiation associated protein 1 (GDAP1) gene have been associated with demyelinating and axonal forms of Charcot-Marie-Tooth (CMT) disease, the most frequent hereditary peripheral neuropathy in humans." (PMID 34440148, 2021).
Charcot-Marie-Tooth disease (continued). "These numbers suggest that RFC1 is among the three most common genetic causes of Charcot-Marie-Tooth disease in Finland together with PMP22 duplication and p.His123Arg in GDAP1." (PMID 34600502, 2021). "Given the high GDAP1 neural expression, we chose MNs and NPs, as cellular models to investigate its functions, and evaluate its role in Charcot-Marie-Tooth disease development." (PMID 34440148, 2021). "The ganglioside-induced differentiation-associated protein 1 gene (GDAP1), which is involved in the Charcot-Marie-Tooth disease (CMT), the most commonly inherited peripheral neuropathy, encodes a protein anchored to the mitochondrial outer membrane." (PMID 22200116, 2011). "Our findings highlight the critical role of GDAP1 in preserving MCSs and the structural integrity and functional capacity of peripheral nerves and propose PPARγ as a potential drug target for GDAP1-related Charcot-Marie-Tooth disease." (PMID 39801517, 2024). "Charcot-Marie-Tooth disease (CMT) is the most common inherited peripheral polyneuropathy in humans, and its subtypes are linked to mutations in dozens of different genes, including the gene coding for ganglioside-induced differentiation-associated protein 1 (GDAP1)." (PMID 37058526, 2023). "The high intra-species and inter-species variability, together with the complexity of GDAP1 molecular mechanisms involved in Charcot-Marie-Tooth disease, may limit the animal models’ reliability." (PMID 34440148, 2021). "Interestingly, naturally occurring mutations have been reported in AH-containing fission-inducing proteins and related to diseases such as centronuclear myopathy (amphiphysin 2), Charcot-Marie-Tooth disease (GDAP1), Parkinson’s disease (α-synuclein)." (PMID 31921835, 2019). "GDAP1 is an outer mitochondrial membrane protein involved in Charcot-Marie-Tooth (CMT) disease." (PMID 28220846, 2017). "Interestingly, naturally occurring mutations have been reported in amphipathic helix-containing membrane fission-inducing proteins and are the basis of human diseases such as centronuclear myopathy (amphiphysin 2), Charcot-Marie-Tooth disease (GDAP1), Parkinson’s disease (α-synuclein)." (PMID 37371051, 2023). "GDAP1 mutants found in patients with the Charcot-Marie-Tooth disease do not target mitochondria and lack mitochondrial cleavage activity." (PMID 30563106, 2018).
neuropathy (11 papers, 2014 to 2025). A disorder affecting the nervous system that manifests with pain, tingling, numbness, and/or muscle weakness. "Vocal cord paralysis has been reported as an early, severe, and frequent symptom of GDAP1-associated neuropathy [CMT4A], often followed by diaphragmatic dysfunction, and in both AD and AR inheritance forms of CMT2A (mutations in the MFN2 gene)." (PMID 37966693, 2023). "Available data suggest that GDAP1 autosomal recessive (AR) inherited mutations lead to severe, early-onset neuropathy with axonal collapse and demyelinating variations." (PMID 37966693, 2023). "Two patients with recessive mutations in GDAP1 presented with an early onset, severe neuropathy associated with vocal cord paralysis." (PMID 31827005, 2020). "GDAP1 autosomal recessive inherited mutations cause a severe, early onset neuropathy often resulting in wheelchair-dependency in the second or third decade." (PMID 31179332, 2019). "Vocal cord paralysis has been reported as an early, severe and frequent symptom of GDAP1-associated neuropathy [CMT4A], often followed by diaphragmatic dysfunction, and in both AD and AR forms of CMT2A (mutations in the MFN2 gene)." (PMID 28190646, 2017). "Yet milder axonal dominant variant (CMT2K) has also been reported, which suggest different pathogenic consequences of the GDAP1 mutant protein and mechanisms of the neuropathy." (PMID 25860513, 2015). "Vocal cord palsy with GDAP1 neuropathy has been observed in patients with p.Q163X and p.S194X mutations." (PMID 37966693, 2023). "Alterations in GDAP1 gene should be evaluated as CMT causing variants in the Vietnamese population, predominantly axonal form of neuropathy in CMT disease." (PMID 31179332, 2019). "Dominant and recessive mutations in GDAP1 cause demyelinating (CMT4A), or axonal (AR-CMT2 or CMT2K) neuropathies." (PMID 28553203, 2017). "In contrast, our Gdap1-/- mouse model expressed an earlier onset in neuropathy-related signs as indicated by motor behavior abnormalities at the age of 3 months and electrophysiological changes in 5-months-old animals." (PMID 25860513, 2015). "To investigate the biological and functional consequences of lack of GDAP1 and to gain insight into the pathophysiology of the GDAP1-related neuropathies we have generated a Gdap1 knockout mouse." (PMID 25860513, 2015). "The child’s parents were also tested, and the results were unremarkable for this pathogenic variant of the GDAP1 mutation gene without clinical manifestation of the neuropathy." (PMID 37966693, 2023). "Thus, the pathophysiology of GDAP1-related neuropathies may involve complex cellular interactions between mitochondrial network and ER, oxidative stress and Ca2+ homeostasis, associated with mitochondrial dynamics and distribution." (PMID 25860513, 2015).
neuroblastoma (10 papers, 2015 to 2025). Neuroblastoma (NB) is the most common solid, extracranial childhood tumor. "Knockdown-rescue studies in a mouse neuroblastoma cell line showed that expression of disease-associated N-terminal mis-sense mutants of GDAP1 in GDAP1-silenced cells was able to restore peroxisomal fission, but not mitochondrial fission." (PMID 40621503, 2025). "The present study has addressed the cause and functional consequences of the decrease in SOCE activity caused by GDAP1 deficiency in neuroblastoma cells." (PMID 28220846, 2017). "The GDAP1 gene (8q21) coding for the ganglioside differentiation-associated protein 1 was first characterized as the gene whose expression is tightly correlated with the differentiation of the neuroblastoma cells." (PMID 36140714, 2022). "In comparison, mitochondria in CMT2K’s axons could be elongated, as described in another study that detected that GDAP1 knockdown in neuroblastoma cells causes elongated mitochondria with tubular morphology." (PMID 34366782, 2021). "GDAP1 silencing in neuroblastoma cells or genetic disruption in mice caused a similar change in Ca2+ homeostasis: a failure to activate the store-operated calcium entry (SOCE) process, a cytosolic Ca2+ entry mechanism activated by a decrease in ER- Ca2+ levels." (PMID 30669311, 2019). "Indeed, GDAP1 deficiency reduced contacts between mitochondria and ER in neuroblastoma cells, and overexpression of GDAP1 in HeLa cells increased co-localization between both organelles." (PMID 30669311, 2019). "In this work, we used neuronal GDAP1 KD in human SH-SY5Y neuroblastoma cells and patient-derived cells to study the pathophysiology of CMT4A." (PMID 35662277, 2022). "We checked if, similarly to neuroblastoma cells, a decreased amount of GDAP1 in HeLa cells also resulted in alterations to the Golgi morphology." (PMID 33477664, 2021). "It has been shown that GDAP1-knockouts in either human neuroblastoma SH-SY5Y cells or in mice motor neurons exhibit a defect in store-operated calcium entry (SOCE), a calcium cell-entry pathway." (PMID 33477664, 2021). "Here we investigated the effect of altering GDAP1 expression levels (either reduced or overexpressed) in the SH-SY5Y cell line derived from human neuroblastoma." (PMID 33477664, 2021). "The GDAP1 mRNA is one of 10 mRNAs that are highly expressed in the Neuro2a cell line (a mouse neuroblastoma cell line) following neurite-like differentiation." (PMID 33477664, 2021). "In conclusion, in neuroblastoma cell lines, SOCE deregulation affects cellular respiration in cells carrying recessive GDAP1 mutations inside the α-loop domain." (PMID 30669311, 2019). "Disruption of the mitochondrial network in a neuroblastoma model of GDAP1-related CMT has been shown to decrease Ca2+ entry through the store-operated calcium entry (SOCE), which caused a failure in stimulation of mitochondrial respiration." (PMID 30669311, 2019). "Ca2+ release from de ER and Ca2+ inflow through SOCE in neuroblastoma cells result in a Ca2+-dependent upregulation of respiration which is blunted in GDAP1 silenced cells." (PMID 28220846, 2017). "We have recently demonstrated that GDAP1 silencing in the neuroblastoma SH-SY5Y cells reduces Ca2+ inflow through store-operated Ca2+ entry (SOCE) upon mobilization of endoplasmic reticulum (ER) Ca2+, likely in association with the abnormal distribution of the mitochondrial network." (PMID 25860513, 2015). "Thus, TEM analysis of a neuroblastoma cell line suggested that GDAP1 protein may also influence the structure and function of the Golgi." (PMID 33477664, 2021). "We show that mitochondrial Ca2+ uptake regulates SOCE activity in neuroblastoma cells, presumably by preventing its Ca2+-dependent inactivation, and that a failure to take up Ca2+ in mitochondria next to the sites of SOCE channels causes suppression of SOCE in GDAP1 deficient cells." (PMID 28220846, 2017).
neuroblastoma (continued). "This might be related to the altered distribution of the mitochondrial network within the cell associated with abnormal movement of mitochondria along the cytoskeleton towards the ER and subplasmalemmal microdomains in neuroblastoma cells having residual GDAP1 expression." (PMID 25860513, 2015). "Next, we examined the effect of Glu222Lys amino-acid substitution on the GDAP1 expression, cell viability, sensitivity to H2O2 and the differentiation process of the neuronal cell line (human neuroblastoma SH-SY5Y cell line)." (PMID 36140714, 2022).
Charcot-Marie-Tooth disease type 4A (5 papers, 2011 to 2024). "In Charcot-Marie-Tooth type 4A disease (CMT4A), causative mutations were identified in GDAP1 (ganglioside induced differentiation associated protein 1)." (PMID 32183277, 2020). "Four of these decedents had compound heterozygous P/LP/VUS variants in genes associated with recessive disorders, including CFTR (cystic fibrosis), BCKDHA (maple syrup urine disease), MPDZ (congenital hydrocephalus-2), and GDAP1 (Charcot-Marie-Tooth disease, type 4A)." (PMID 38229148, 2024). "None of these features were found on the patients.GDAP1 gene sequencing showed a homozygous point mutation (p.Q163X), which led us to the diagnosis of Charcot-Marie-Tooth disease, type 4A." (PMID 26848201, 2015).
Alcohol Use Disorder (4 papers, 2025). "A gene that has been linked to alcohol use disorder in recent studies is the ganglioside‐induced differentiation‐associated protein 1 (GDAP1) gene." (PMID 40251787, 2025). "From a clinical point of view, inconstant hypermethylation of the DAT was also reported in the post-exposure withdrawal phase of alcohol use disorder, while methylation of MAOA and hypomethylation of NR2B and GDAP1 were observed in positive relationship to the severity of the alcohol use disorder." (PMID 41153345, 2025).
axonal neuropathies (4 papers, 2015 to 2024). "Here we present two female patients, daughters of consanguineous parents, with an early onset of symptoms, and an axonal neuropathy in whom a GDAP1 Q163X mutation was found." (PMID 26848201, 2015). "However, electrophysiological studies indicate that especially in the more severe patients the GDAP1 mutations induce primary axonal neuropathy with secondary demyelination." (PMID 25860513, 2015). "Dominant GDAP1 mutations are associated with mild axonal neuropathy with late onset and slow disease progression, the extent and severity of proximal weakness is less pronounced compared with recessive mutations, and the electrophysiology findings are variable 12,13." (PMID 26848201, 2015). "Among them, GDAP1-related CMT is one of the most frequent recessive axonal neuropathies in many populations." (PMID 39801517, 2024). "In GDAP1-CMT patients, axonal neuropathy is associated with loss of axons in sural nerve biopsies." (PMID 25860513, 2015). "Axonal neuropathy revealed by our electrophysiological studies in 5-months-old Gdap1-/- mice could be associated with defects in other motor neuron-derived structures affected by the absence of GDAP1." (PMID 25860513, 2015). "Interestingly, at 5-months Gdap1-/- mice showed a significant reduction of CMAP amplitude obtained for distal (at the ankle) and proximal (at the hip) stimulation, indicative for an axonal neuropathy (p<0.05, Student’s t test)." (PMID 25860513, 2015).